TNF (tumor necrosis factor)
Diseases named in the same sentence as TNF in open-access papers (continued):
Sharing a sentence is not in itself a finding about the gene and the disease.
pulmonary fibrosis (continued). "In the absence of FOXM1, the p38 MAPK pathway is activated in macrophages leading to production of pro-fibrotic mediators IL-1β, IL-6 and TNF-α that directly stimulate fibroblast activation and survival, exacerbating pulmonary fibrosis." (PMID 32271749, 2020). "Previous studies have indicated that multiple cytokines, including TGF-β1, IL-1β, TNF-α, IL-17, IL-27, IL-13, and IL-32, are overexpressed in pulmonary fibrosis." (PMID 33097029, 2020). "Investigations have demonstrated that antagonists of TNF prevent fibrosis in mouse models of silica-induced and bleomycin-induced pulmonary fibrosis." (PMID 31881890, 2019). "Considering the role of TNFα in the relationship between silicotic lung fibrosis and Npnt levels, TNF-α is known to be involved in initial inflammatory responses that form silicotic nodules and in the recognition of silica particles by alveolar macrophages." (PMID 31130697, 2019). "ART can significantly downregulate the expression of TGF-β1 and TNF-α in rats with pulmonary fibrosis, thereby mitigating the pulmonary fibrosis." (PMID 31847860, 2019). "This approach significantly reduced the expression of IL-1, TNFα and TGFβ mRNA and consequentially prevented acute radiation pneumonitis and chronic radiation-induced pulmonary fibrosis." (PMID 30590649, 2019). "TNF-α is one of the most relevant cytokines to the biological events in silicosis such as inflammation and silica-induced pulmonary fibrosis, regulating cell proliferation, differentiation, and apoptosis." (PMID 30643011, 2019). "Previous studies have demonstrated that infliximab, a TNF-α antagonist, improved the degree of pulmonary fibrosis induced by BLM in rats." (PMID 29997685, 2018). "Elevated levels of TGF-β and TNF-α have been found in the lungs of animals in experimental models of pulmonary fibrosis and in patients with IPF." (PMID 29997685, 2018). "TNF-α, which stimulates fibroblasts and facilitates collagen production, has been demonstrated to be elevated in the lungs of patients with idiopathic pulmonary fibrosis." (PMID 29861433, 2018). "In vivo experiments showed that BLM combined with SCU in the treatment of mice bearing H22 ascites tumor prolonged the survival time, alleviated BLM-induced pulmonary fibrosis, reduced the production of TNF-α; IL-6, and the levels of MDA and MPO." (PMID 29962947, 2018). "Our results revealed significant enrichment of proteins in pathways that have been previously associated with immunity/autoimmunity, including “apoptosis”, “TNF-α signaling”, “lung fibrosis”, “IL-1 pathway”, “toll-like receptor (TLR) signaling”, “E." (PMID 29606147, 2018). "Bleomycin-induced pulmonary fibrosis increases lung IL-6 and TNF-α levels and subsequently elevates MCP-1 levels; MCP-1 then recruits macrophages to the lung tissue." (PMID 29772024, 2018). "This toxicity is related to several inflammatory mediators including transforming growth factor-beta (TGF-beta) and tumor necrosis factor-alpha (TNF-alpha), chemokines among others, which cause severe lung fibrosis as side effect." (PMID 29854623, 2018). "IL-1β can drive the progression of pulmonary fibrosis, and it is known to mediate the release of other inflammatory cytokines such as TNF-α and IL-6." (PMID 30087305, 2018). "Zhang and colleagues showed that, in a mouse model of bleomycin‐induced fibrosis, neutralizing TNF‐α resulted in lower eosinophil numbers and less development of pulmonary fibrosis (i.e., lower hydroxyproline content)." (PMID 29721324, 2018). "In the pathogenesis of pulmonary fibrosis, expression and secretion of pro-inflammatory and pro-fibrotic mediators such as IL-1β, TNFα and TGF-β1 play a crucial role." (PMID 30510259, 2018). "It has been reported that pirfenidone, which is an anti-fibrotic agent used for idiopathic pulmonary fibrosis, also exhibits anti-TNF-α and anti-TGF-β1 effect." (PMID 28507324, 2017).
pulmonary fibrosis (continued). "Subsequently, we found that MMP14 abundant in extracellular matrix and TNF signaling pathway was significantly increased in the pulmonary fibrosis model induced by bleomycin via RT-PCR verification." (PMID 29050340, 2017). "Mice that overexpressed IL-17, TNF-α and IL-1β in the lung developed highly progressive pulmonary fibrosis." (PMID 28466866, 2017). "The current results agreed with researchers who found increases in TNF, IL-1β, and IL-6 in bronchoalveolar lavage fluid in pulmonary fibrosis rat model." (PMID 28883083, 2017). "Taken together, however, the results of this study indicate that midkine is potentially involved in the development of pulmonary fibrosis by regulating inflammatory cell migration into the lung and expression of TNF‐α and TGF‐β." (PMID 28811360, 2017). "The pro-inflammatory cytokines are known to play a significant role in the processing of pulmonary fibrosis, including TNF-α and IL-6." (PMID 28245556, 2017). "A number of TNF-targeted therapies to treat pulmonary fibrosis are currently under clinical investigation." (PMID 26971883, 2016). "Increased expression of TNF-α and IL-1β has been found in the lungs of patients and animal models of pulmonary fibrosis." (PMID 26977316, 2016). "TNF-α has been demonstrated to play a key role in activating molecular pathways leading to pulmonary fibrosis." (PMID 27527840, 2016). "In this context, a panel of pro-inflammatory cytokines including TNF-α, IL-1α, IL-1β, and IL-6 have been shown to be pro-fibrotic factors in both mouse and human lung fibrosis models." (PMID 27814727, 2016). "TNF-α appears to play important roles in various fibrosis animal models, such as bleomycin- or silica-induced lung fibrosis and CCl4-induced liver fibrosis, as well as a number of human fibrotic diseases, such as IPF and asbestosis." (PMID 27814727, 2016). "The role of cytokines in fibrosis formation has become a hot spot of research and IL-6 has ability to promote fibrosis formation alone or together with TNF-α in bleomycin-induced pulmonary fibrosis." (PMID 28194150, 2016). "Although lots of cytokines were regulated independently of HBoV status, several cytokines associated with lung fibrosis and tumour development, e.g., EGF, VEGF, TARC (CCL17), TNF-α, TNF-β, TIMP-1, were clearly upregulated in the HBoV-positive cohort." (PMID 26807786, 2016). "Inhibiting TNFα at this point has been shown to lead to less fibrosis in models of kidney, liver, heart, and lung fibrosis." (PMID 26618160, 2015). "A number of inflammatory cytokines including TNFα and IL-1β are overexpressed in preclinical models of lung fibrosis and in lung tissue from IPF patients." (PMID 26231702, 2015). "We found that lung IL-6 and TNF-α levels were significantly increased after BLM administration in the BLM–induced murine pulmonary fibrosis model." (PMID 26497260, 2015). "The fact that anti-inflammatory drugs such as corticosteroids are harmful to pulmonary fibrosis patients indicates that TNFα is probably involved in attempted resolution." (PMID 26618160, 2015). "In murine models of lung fibrosis induced by bleomycin or silicium oxide particles, the TNF-α level was increased in lung tissue." (PMID 26596627, 2015). "Intra-tracheal delivery of recombinant TNF-α can ameliorate established pulmonary fibrosis, partially via inducing Fas-mediated fibroblast apoptosis." (PMID 26962470, 2015). "TNF-α injection induced changes mimicking those observed in lung fibrosis, such as increased number of fibroblasts, collagen deposits and necrosis." (PMID 26596627, 2015). "TNF-α is a key cytokine in pulmonary fibrosis, which induces expression of adhesion molecule, recruitment of inflammatory cells into the lungs and synthesis of other cytokines." (PMID 25465226, 2014).
pulmonary fibrosis (continued). "A-MWCNTs delivered to the lungs of mice by OPA had reduced mRNA or protein levels of IL-1β, IL-6, OPN and TNF-α relative to U-MWCNT at 1 or 28 days post-exposure and A-MWCNTs caused less lung fibrosis in mice relative to U-MWCNTs." (PMID 25216247, 2014). "TNF-α plays an important role in the pathogenesis of pulmonary fibrosis by increasing the production of TGF-β1, which in turn increases collagen synthesis by fibroblasts and differentiation of fibroblasts to myofibroblasts." (PMID 25216247, 2014). "TNF-α is a pro-inflammatory cytokine that is critical in diverse cellular events and is also considered to be critical in the development of lung fibrosis." (PMID 23407465, 2013). "Anti-TNF-α also markedly suppressed BLM-induced lung fibrosis and decreased the expression of TGF-β and MCP-1 in the lung." (PMID 23997916, 2013). "Bleomycin-induced mouse lung fibrosis models have demonstrated an MSC stimulated reduction in pulmonary fibrosis via inhibition of pro-fibrotic cytokines TNF-α and IL-1 through a paracrine mechanism." (PMID 23350749, 2013). "Tumor necrosis factor (TNF)-α is a proinflammatory cytokine with many biological properties and is critical in the development of pulmonary fibrosis." (PMID 21961991, 2011). "While TNF-α is reported to be a major cytokine for the development of pulmonary fibrosis, recent studies show that TNF-α both induces and protects against disease processes." (PMID 21961991, 2011). "Although the mechanisms by which PN attenuates lung fibrosis are unclear, this study shows that TNF-α and IL-6 cytokine levels are significantly reduced by PN in alveolar macrophage culture." (PMID 21423633, 2011). "Elevated levels of pro-inflammatory cytokines and chemokines such as TNF, IL-6 and CXCL8 are associated with several human diseases including cystic fibrosis, pulmonary fibrosis and AIDS." (PMID 20507572, 2010). "Other studies have documented possible effects of TNF-α on the development of pulmonary fibrosis through chronic lung inflammation and activation of the elastolytic enzymes." (PMID 19706153, 2009). "We chose to test cytokines and factors known for their different activities on the development of lung fibrosis: proinflammatory (IL-1β and TNF-α), profibrotic (IL-4 and TGF-β) and antifibrotic mediators (IL-9 and PGE-2)." (PMID 16045809, 2005). "It has been demonstrated, for instance, that macrophages obtained from animal models of silicosis or from patients with lung fibrosis overproduce pro-inflammatory cytokines and growth factors such as TNF-α, IL-1, PDGF and TGF-β." (PMID 16212659, 2005). "TNF-alpha, is a proinflammatory cytokine with many biologic properties thought to be critical in the development of pulmonary fibrosis." (PMID 16159396, 2005). "Rats treated with silica particles developed chronic and progressive inflammation accompanied by an overproduction of TNF-α as well as an intense lung fibrosis." (PMID 16212659, 2005). "Subsequent correlation analysis indicated that Lactobacillus was significantly positively associated with physiological data, including serum IL‐1β, TNF‐α, TGF‐β, and indexes related to pulmonary fibrosis, and Muribaculaceae was obviously negatively associated with physiological data." (PMID 41509197, 2026). "Retinoids attenuated lung fibrosis mainly by inhibiting the inflammatory response through downregulating the expression of NF-κB and by inhibiting the release of the downstream cytokines TNF-α, INF-γ, and IL-13." (PMID 40508111, 2025). "Furthermore, we identified the involvement of the TNF signaling pathway and Toll-like receptor (TLR) signaling pathway, which has previously been linked to immune-related diseases such as idiopathic pulmonary fibrosis." (PMID 40224483, 2025). "Potential Mechanisms: 1) Plasma cell-derived cytokine production: Malignant plasma cells in MM produce multiple cytokines (IL-6, TNF-α, IL-1β) that may trigger pulmonary fibrosis through Th2-mediated immune responses." (PMID 41477374, 2025).
pulmonary fibrosis (continued). "Quercetin can significantly improve lung function in pulmonary fibrosis models by enhancing cell viability, reducing the production of inflammatory cytokines Tumor Necrosis Factor-alpha (TNF-α), Interleukin-6 (IL-6), Interleukin-8 (IL-8), and inhibiting apoptosis." (PMID 40697927, 2025). "In patients with severe disease, fibrosis-related cytokines such as Transforming Growth Factor (TGF-β), Tumor Necrosis Factor (TNF-α), and Interleukin (IL)-6 are significantly elevated in peripheral blood, which is closely associated with the development of pulmonary fibrosis." (PMID 40427668, 2025). "The results showed that pulmonary fibrosis may be mitigated following AT-MSCs transplantation in PQ-poisoned mice by suppressing the synthesis of pro-inflammatory cytokines (interleukin-6 and tumor necrosis factor-alpha) in the lung tissues of the animals." (PMID 40665395, 2025). "In this study, we verified that diazepam can effectively inhibit inflammation in pulmonary fibrosis; specifically, diazepam can effectively inhibit the expression of the inflammatory cytokines IL-4, IL-6 and TNF-α and effectively alleviate the occurrence of pulmonary fibrosis." (PMID 38875245, 2024). "Additionally, the BALF concentrations of TNFα, interleukin-6 (IL-6), osteopontin, interferon-γ (IFNγ), and SP-D were substantially lower in TG mice with lung fibrosis than in their WT counterparts." (PMID 39329706, 2024). "IL-6 and TNF-α are proinflammatory factors but also inducers of pulmonary fibrosis." (PMID 38914619, 2024). "Iloprost prevents pulmonary fibrosis, possibly by upregulating anti-fibrotic mediators (interferon γ and C-X-C motif chemokine ligand 10) and downregulating pro-inflammatory and pro-fibrotic cytokines (tumor necrosis factor α, IL-6, and TGF-β1)." (PMID 38878214, 2024). "The drug group exhibited significantly elevated expression of transforming growth factor β (TGF-β), hydroxyproline (HYP; which can indicate the degree of pulmonary fibrosis), Tumor Necrosis Factor α (TNF-α), and Interleukin 6 (IL-6) gene compared to the control group." (PMID 37580529, 2023). "For example, in idiopathic pulmonary fibrosis, a variety of factors can stimulate their differentiation into myofibroblasts including tumor necrosis factor-α (TNF-(α), transforming growth factor-β1 (TGF-β1), endoplasmic reticulum (ER) stress, Hedgehog (HH), and Wingless/integrated (Wnt) signaling." (PMID 36749355, 2023). "Therefore, TNF-α is related to the early stage of pulmonary fibrosis and EMT and ferroptosis can be regulated by TNF." (PMID 36672671, 2023). "Moreover, RUP notably repressed macrophage and mast cell infiltration and inhibited expression of TNF-α and mast cell degranulation in a rat model of lung fibrosis." (PMID 36811777, 2023). "JWH133 activated CB2R regulating the inflammatory response, and subsequently reduced pulmonary fibrosis in mice.The ELISA results showed significantly higher levels of inflammatory markers TNF-α, IL-6, and IL-1β in the serum of the BLM group, which decreased after the administration of JWH133." (PMID 37957604, 2023). "Indeed, one main etiology of pulmonary fibrosis is acute and/or chronic inflammation via the release of lung proinflammatory cytokines and chemokines (such as TNF-α, IL-1β, IL-6, and IL-8) along with NF-κB." (PMID 36830999, 2023). "In addition, Longidaze inhibited the inflammatory response in pulmonary fibrosis, and decreased the levels of IL-6, TNF-α, and hyaluronic acid in lung tissue and the recruitment of inflammatory cells into lung tissue." (PMID 37763335, 2023). "Spn infection may also cause the depletion of Regulatory T cells by upregulating the response of Th1/2 cytokines (TNF-α, IL-6), leading to the deterioration of lung fibrosis in mice overexpressing TGF-β1." (PMID 38007420, 2023).
pulmonary fibrosis (continued). "Similarly, in an established model of lung fibrosis, RP-832c significantly decreased lung fibrosis and significantly decreased inflammatory cytokines TNF-α, IL-6, IL-10, IFN-γ, CXCL1/2, and fibrosis markers TGF-β1 and MMP-13." (PMID 37174654, 2023). "Nonetheless, there is evidence that TNF-α may be profibrotic in murine models of renal and lung fibrosis, while the evidence in IgG4-RD is limited." (PMID 36831337, 2023). "However, other reports implicate an antagonistic relationship as chronic overexpression of TNFα not only protected mice from BLM-induced lung fibrosis, but also accelerated resolution of this pathology through a reduction in profibrotic lung macrophages." (PMID 37849737, 2023). "Afterward, we used Metascape for the pathway enrichment analysis of this network, and we found that the most significant terms within the cluster consisting of EGF, IL-1β, IL-3, TNF-α, CCL2 were associated with lung fibrosis and proinflammatory/fibrotic mediators." (PMID 36733673, 2023). "Moreover, naringenin was shown to have a significant therapeutic effect on Mycoplasma pneumoniae-induced lung injury in mice by inhibiting pulmonary fibrosis and inhibiting the secretion of inflammatory cytokines such as IL-6, IL-1β, TNF-α, and TGF-β." (PMID 38074219, 2023). "acute lung injury score, fibrosis score in mice with BLM-induced pulmonary fibrosis were increased, and the inflammatory markers such as IL-6, TNF-α and monocyte chemoattractant protein-1 in bronchoalveolar lavage fluid were also increased, while the anti-inflammatory cytokine IL-10 was decreased." (PMID 38007420, 2023). "It was found that the affinity was similar to the docking scores of IL6 and TNFα, indicating that these key active components may play a key role in the treatment of pulmonary fibrosis." (PMID 35370663, 2022). "However, a recent study suggests that TNF-α can resolve lung fibrosis by targeting the profibrotic macrophages in the rodent model of lung fibrosis." (PMID 36145551, 2022). "Indeed, TNF-α is a factor involved in SSc that favors pulmonary fibrosis and pulmonary arterial hypertension." (PMID 36614095, 2022). "Similarly, using Masson staining and analysis with Ashcroft's lung fibrosis score, it was found that the lungs of TNF-Tg mice, including the vicinity of the bronchi and alveoli, had severe fibrous tissue proliferation." (PMID 35600883, 2022). "In addition, network analysis and visualization revealed pulmonary healing signaling pathways, pulmonary fibrosis idiopathic, and IL-1/TNF signaling pathway with a significant positive correlation." (PMID 36381194, 2022). "Therefore, the treatment strategy of inhibiting TNF production is of great significance in the treatment of pulmonary fibrosis." (PMID 35548340, 2022). "It indicated that FZHY might inhibit experimental pulmonary fibrosis via down-regulate the activation of pro-inflammatory macrophages expressing TNF-α." (PMID 35548340, 2022). "Interestingly, the role of proinflammatory cytokine TNF-α in lung fibrosis has been investigated with contradictory reports, two studies showing permanent expression of TNF-α by alveolar epithelial cells leading to fibrotic lesions in the mice lung." (PMID 36145551, 2022). "Studies have shown that TNF-α plays an important role in pulmonary interstitial fibrosis." (PMID 36524110, 2022). "MiR-140 downregulates OGN, resulting in activation of the Wnt signaling pathway and further modulating the expression of genes associated with the progression of pulmonary fibrosis in mouse fibroblasts, including transforming growth factor beta (TGF-β1), TNF-α and CTGF included." (PMID 36421687, 2022). "The controversial role of TNF-α in lung fibrosis has been discussed previously." (PMID 35082682, 2021). "Therefore, endogenous TNF-α and its receptors seem to be required for the development of lung fibrosis." (PMID 35082682, 2021). "Like TNF-α, IL-17 has been shown to play an important role in pulmonary fibrosis." (PMID 34258628, 2021).